CTLA4 (cytotoxic T-lymphocyte associated protein 4)
Diseases named in the same sentence as CTLA4 in open-access papers (continued):
Sharing a sentence is not in itself a finding about the gene and the disease.
cancer (continued). "Thus, six major ICs for cancer immunotherapy were analyzed in this work, namely CTLA4, PDCD1, CD274, ICOS, LAG3, and CD40." (PMID 37215135, 2023). "The introduction and clinical implementation of T cell-directed immunomodulators blocking immune checkpoints CTLA-4, programmed cell death-ligand 1 (PD-L1) and PD-1 have rejuvenated the field of tumor immunology and revolutionized cancer treatment far beyond their impressive clinical activity." (PMID 37767098, 2023). "Both the CTLA-4 and PD-1 pathways act to prevent the hyperactivation of the immune system, and the inhibition of these inhibitory molecules has been shown to be capable of mediating robust immune activation against cancer." (PMID 36672243, 2023). "Immune checkpoint blockade has the broadest impact in different types of cancer immunotherapy, with some antibodies against the cytotoxic T lymphocyte antigen 4 (CTLA4) or programmed cell death 1 (PD1)—PD1 ligand 1 (PD-L1) axis being approved for many different cancers." (PMID 38093288, 2023). "Therefore, an inherent capacity of SDT to release these Treg and CTLA-4 breaks on antitumour immunity offers unique benefits for a cancer therapy." (PMID 36319895, 2023). "PD-1 and CTLA-4 are expressed by activated T cells and most studies on these pathways have focused on their impact on effector responses which has formed the basis for checkpoint blockade in cancer." (PMID 36960049, 2023). "CTLA4 was the first immune checkpoint to be targeted for cancer immunotherapy." (PMID 37435963, 2023). "Therefore, only cancer patients treated with PD-(L) or CTLA4 were included in this study, and the relationship between GNRI and anti-TGF-β/PD-L1 bispecific antibodies needs to be further investigated." (PMID 38024341, 2023). "Additionally, cytotoxic T-lymphocyte associated protein 4 (CTLA4), which is an important T-cell immune regulation factor and a well-known immune checkpoint target in cancer immunotherapy, was also upregulated in high PFKP cancer samples." (PMID 37833332, 2023). "Antibodies targeting the checkpoints PD-L1, PD-1 and CTLA-4 are currently being used or are in clinical trials for treating many cancers including CRC; however, there are a number of problems associated with treating cancer patients with immunotherapies." (PMID 37847301, 2023). "Although ICIs have made great breakthroughs in cancer treatment, the low proportion of beneficiaries based on PD-1/PD-L1/CTLA-4, the high proportion of irAEs, and the high cost of treatment are the main problems to be solved urgently in current immunotherapy limited." (PMID 37226190, 2023). "Similarly, CTLA4, an inhibitory receptor that is expressed in T cells, inhibits T-cell activation, highlighting its effectiveness in cancer treatment." (PMID 37142983, 2023). "CTLA‐4 and PD‐1 are key immune checkpoint receptors that are targeted in the treatment of cancer." (PMID 36727298, 2023). "Expression of CTLA-4 enables cancer cells to evade antitumor T cell responses and may reduce the anti-cancer immune response, making tumors more likely to spread." (PMID 38406785, 2023). "IMGT/mAb-DB lists eight mAbs targeting CTLA4 for cancer immunotherapy." (PMID 37215135, 2023). "Several immune checkpoint proteins, such as programmed cell death protein 1 (PD-1), programmed cell death ligand 1 (PD-L1), and cytotoxic T lymphocyte-associated protein 4 (CTLA-4), enable peripheral immune tolerance under physiological conditions although often become coopted in the cancer context." (PMID 37711295, 2023). "Cancer management still requires more potent and safer treatments, of which immunomodulatory receptors on the lymphocyte surface have started to show promise in new cancer immunotherapies (e.g., CTLA-4 and PD-1)." (PMID 38139340, 2023).
cancer (continued). "Overall, immune checkpoint expression may be dysregulated in the HCC microenvironment, and cancer immunotherapy based on CTLA-4, PDCD1 and PD-L1 inhibitors may achieve antitumor therapeutic effects by improving Treg cell-mediated immune responses." (PMID 37426702, 2023). "Some researchers believe that the overexpressed PD-L1 on cancer cells can suppress the expression of CTLA-4, and the retention of CTLA-4 may weaken the immune activation effect of PD-L1 blockade." (PMID 37926852, 2023). "This vaccine has been reported to cause the induction of CD8+ T cell infiltration in a CXCL10 manner and up-regulation of immune inhibitory checkpoints such as CTLA-4, thus showing that anti-cancer vaccines are interesting leads and require further investigation." (PMID 37443821, 2023). "Despite this, the targeting of CTLA-4 remains a valuable approach for cancer immunotherapy owing to its remarkable long-term benefits provided the irAEs could be effectively managed." (PMID 37828948, 2023). "The high expression of CTLA-4 also weakened T cell function in cancer." (PMID 37355637, 2023). "Immunotherapies like CTLA-4/PD-1 blockage have strictly made progress for anti-cancer treatment." (PMID 37595258, 2023). "In cancer patients, this condition often results from inadequate interruption or suspension of ongoing steroid therapy, leading to altered adrenal gland function or, rarely, from the use of immunotherapy drugs (anti-CTLA4 and anti-PD1)." (PMID 37623012, 2023). "Considering that drugs targeting PD-1 and CTLA-4 have recently received approval for the treatment of several cancers, we evaluated whether the NM-TME classifier could predict patients’ reactions to immunotherapy." (PMID 37095256, 2023). "Therefore, this study investigated the relationships between these three functional polymorphisms and their association with CRC in the Saudi Arabian population and the assessment of the expression profile of CTLA-4 in cancer tissue." (PMID 37107632, 2023). "Additionally, polymorphisms of other genes, e.g., in CTLA4 or CYP1A1, cause an increased incidence of these cancers." (PMID 37242569, 2023). "Other immune checkpoint inhibitors such as CTLA-4 antibody or other anti-cancer drugs may also be considered for the neoantigen-based combination therapy." (PMID 37848417, 2023). "However, the permanent expression of CTLA-4 on cancer cells showed a critical role in cancer cell progression by producing inhibitory signals to weaken the immune response." (PMID 37568193, 2023). "The novel method provided a practical quantitative method for the total of CTLA-4 level in human T cells, which could be widely applicable in studying CTLA-4 as an important drug target for developing immunotherapies for cancer treatment." (PMID 37110545, 2023). "It was the first anti‐CTLA‐4 antibody that received approval for cancer victims." (PMID 36289059, 2023). "By blocking inhibitory signals mediated by surface receptors that are naturally upregulated during activation of antigen-presenting cells (APC) and T cells, predominantly PD-1 and its ligand PD-L1, as well as CTLA-4, such blocking agents have revolutionized cancer treatment." (PMID 37342323, 2023). "Recently, CTLA4 has been extensively studies in the context of cancer immunotherapy." (PMID 37798374, 2023). "Since 2018, immunotherapy, nivolumab, anti-CTLA-4, mechanism, and signal detection might be considered the frontier in pharmacovigilance and cancer research." (PMID 36761953, 2023). "ICIs recover the immune system’s ability to attack cancer through binding to immune checkpoint molecules, such as programmed death receptor-1 (PD-1), programmed death receptor ligand-1 (PD-L1), and cytotoxic T-lymphocyte antigen 4 (CTLA-4)." (PMID 36980950, 2023).
cancer (continued). "Despite this remarkable progress in cancer immunotherapies, multiple lines of evidence indicate that antibody therapies targeting immune checkpoint markers, such as CTLA4, PD-1, or PD-L1, often lead to severe adverse drug reactions resulting from an elevated immune response." (PMID 37205112, 2023). "Within the past decade, T-cell-targeted immunomodulators directed against the immune checkpoints of cytotoxic T-lymphocyte-associated protein 4 (CTLA-4), programmed cell death 1 (PD-1), and its ligand (PD-L1) have revolutionized cancer treatment for several types of tumors." (PMID 36831648, 2023). "This study observed that aberrant expression of IRGs is correlated with cancer development, and the high-risk group showed higher TMB, immune cell infiltration, PD-1, PDL1, and CTLA4 expression, and an intensive immune-related phenotype compared to the low-risk group." (PMID 36834851, 2023). "Currently, ICIs approved by the US Food and Drug Administration (FDA) for the treatment of various types of cancer include PD-1 inhibitors (nivolumab, pembrolizumab, and cemiplimab), PD-L1 inhibitors (atezolizumab, durvalumab, and avelumab), and a CTLA-4 inhibitor (ipilimumab)." (PMID 38067379, 2023). "The immune checkpoint molecules PD-L1, PD-L2, and CTLA-4 play a fundamental role in the regulation of immune response towards cancer cells, by suppressing the activation of protective immune cells, e.g., cytotoxic T cells, and promoting immune surveillance, e.g., by recruiting Tregs." (PMID 36834851, 2023). "CTLA-4 inhibitors, such as ipilimumab or tremelimumab, are currently used for cancer immunotherapy and have shown a survival benefit and/or disease control in the treatment of several advanced cancers." (PMID 37243227, 2023). "Similarly, for TIL, TASL, PD-1, and CTLA-4 expression were highly accurate in 10, 8, and 8 cancer types, respectively." (PMID 37296415, 2023). "It is understood that the binding of CD80 with CTLA-4, a receptor that acts as an important negative regulator of T-cell responses, is favorable for carcinogenesis because cancer cells commonly use the immunosuppressive function of regulatory T cells to avoid immunological attacks." (PMID 37765273, 2023). "Both preclinical and clinical data have shown that CTLA-4 and PD-L1 are key proteins in the regulation of immune checkpoints in cancer cells and their upregulation was shown to negatively affect T-cell response to cancer progression." (PMID 35976445, 2023). "The results of the association between IFN-γ score and ICG indicated that the IFN-γ scores of virtually all of the different cancers that were investigated had a positive association with the expression of TIGIT, IDO1, ICOS, CD86, CTLA4, HAVCR2, PDCD1LG2, and CD48." (PMID 37646041, 2023). "Consequently, immune-checkpoint inhibitors (ICIs) targeting PD-1/PD-L1, and CTLA-4 were the first to be developed, demonstrating unprecedented benefits in selected patients and reshaping the therapeutic landscape for numerous cancers." (PMID 38164130, 2023). "Indeed, cancer immunotherapies aiming at Tex cell reinvigoration, such as monoclonal antibodies targeting PD-1, PD-L1, or CTLA-4, namely checkpoint inhibitors, alone or in combination with CAR-Ts, marked a breakthrough in cancer immunotherapy." (PMID 37046597, 2023). "It was discovered that DCLRE1B expression was positively associated with ICP genes in many types of cancer, especially in PAAD, in which the correlation coefficients of DCLRE1B with PD-1, PD-L1, PD-L2, and CTLA4 were 0.358, 0.577, 0.593 and 0.378, respectively." (PMID 37936074, 2023). "Therefore, a sensitive balance exists between levels of CD28 and CTLA-4 expression in T cells, bringing the final decision to either attack or save cancer cells." (PMID 37185406, 2023). "Only a subset of cancers can benefit from anti-CTLA-4 therapy." (PMID 38005965, 2023).
cancer (continued). "Additionally, the combined use of anti-CTLA-4 mAbs and other anti-cancer molecules has shown positive outcomes, although further work is needed regarding potential adverse effects of such applications." (PMID 37576404, 2023). "Immune checkpoint inhibitors, such as those targeting cytotoxic T lymphocyte‐associated molecule 4 (CTLA‐4), programmed cell death receptor 1 (PDCD1, also named PD‐1), and programmed cell death ligand 1 (CD274, also named PD‐L1), have revolutionized cancer treatment." (PMID 37904707, 2023). "In patients with cancer, CTLA4 overexpression is a key immune evasion mechanism." (PMID 37089933, 2023). "CTLA4 has gained incredible attention after the demonstration that blocking its interactions with its ligands can be highly beneficial to subsets of patients with cancer, paving the way for the immune therapy of cancer with immune checkpoint inhibitors (ICIs)." (PMID 37887068, 2023). "The established immunotherapies that target surface receptors such as CTLA-4 and/or PD-1 with recombinant antibodies have been crucial for cancer treatment, but a significant population of patients fail to respond to these immunotherapies and a low number of them are finally cured." (PMID 38005965, 2023). "Besides, the management of cancer patients was a challenge by advances in immunological treatment, and immune checkpoint molecules, including the PD-1 and CTLA4, govern immune responses within the TME40." (PMID 37217516, 2023). "Immune checkpoint inhibitors work by blocking proteins on the surface of immune cells, such as cytotoxic T-lymphocyte-associated protein 4 (CTLA-4) or programmed cell death protein 1 (PD-1), which can restrict the immune system from identifying and purging and attacking cancer cells." (PMID 37415161, 2023). "Since immune cell checkpoints are key targets for cancer treatment using immune checkpoint blockade (ICB), several checkpoint molecules, including cytotoxic T-lymphocyte-associated protein 4 (CTLA-4), programmed death 1 (PD-1), and programmed cell death-ligand 1 (PD-L1) were evaluated." (PMID 37405952, 2023). "TIDE could predict the outcome of cancer patients treated with first-line anti-PD1 or anti-CTLA4 drugs." (PMID 37784081, 2023). "In addition to anti-CTLA-4, anti-PD-1/PD-L1 is another immune checkpoint inhibitor that has emerged as an important therapeutic tool in the treatment of cancer in recent years." (PMID 37251931, 2023). "Moreover, it is a good strategy that the combined blockade of PD-1 and CTLA-4 by hydrogels is effective against several cancers." (PMID 36587630, 2023). "Even though immunotherapies targeting classical checkpoints such as CTLA-4, PD-1, or PD-L1 have made substantial progress in different types of cancer, a large number of patients remain unresponsive to treatment, suggesting a vacancy for potential mechanisms of inhibitory ligand-receptor pathways." (PMID 37115693, 2023). "Therefore, CTLA-4 has been envisioned as a target of monoclonal antibodies for cancer immunotherapy and CTLA-4 inhibitors." (PMID 37025485, 2023). "Two of the most well-studied checkpoints that may be targeted for the treatment of cancer are the CTLA4 and the PD-1/PD-L1 (programmed death ligand-1) pathways." (PMID 36672615, 2023). "Therefore, there is a huge potential for targeting TIM-3 both alone and in combination with current PD-1 and CTLA-4-based immunotherapy of cancer due to the unique expression and intracellular signaling." (PMID 36677919, 2023). "However, in the ongoing exploration of advanced HCC and other cancers, immunotherapy methods increasingly focus on immune checkpoint inhibitors (ICIs), such as CTLA-4, PD-1 and PD-L1, which lock the immune checkpoint inhibition pathways." (PMID 37745297, 2023). "Correlatively, recent cancer studies have shown that treatment with anti–CTLA-4 results in a reduction of intratumoral Tregs, representing a noncanonical mechanism that may contribute to therapeutic efficacy." (PMID 37345660, 2023).
cancer (continued). "Additionally, is the recombinant oncolytic virus loaded with the anti PD-1/ CTLA-4 antibody gene effective against cancer?" (PMID 36604694, 2023). "Since anti-CTLA-4 drugs are currently available for cancer immunotherapy, this might be a promising approach for future CHB treatment." (PMID 37243227, 2023). "Importantly, higher PD-L1 and CTLA4 expression levels were observed in the PTPRD/PTPRT mutant cancer patients, compared with WT patients, suggesting that ICI treatment is more applicable for PTPRD/PTPRT mutant cancer patients." (PMID 36248841, 2022). "More than half of the reported cancers in CTLA-4 patients are EBV-associated, which observation (including additional virus-related cancer cases) leads to the speculation that the CTLA-4 patients fail at controlling (i.a. oncogenic) viruses." (PMID 36405723, 2022). "Immune checkpoint inhibitors (ICI), including cytotoxic T-lymphocyte-associated protein 4 (CTLA-4), programmed cell death-1 (PD-1), and programmed cell death ligand-1 (PD-L1) antibodies, are arguably the most important development in cancer therapy in the past decade." (PMID 36330095, 2022). "In addition to CTLA-4– and PD-1/PD-L1–targeted cancer immunotherapy, LAG3 (lymphocyte activation gene-3, CD223) is the third clinically targeted inhibitory receptor." (PMID 35651784, 2022). "Mice lacking the iNKT cell subset, compared with wild-type mice, respond to CTLA-4 blockade with markedly increased cure rate and overall survival, indicating that iNKT cells might play a role in efficacy of cancer immunotherapy." (PMID 35677057, 2022). "Combination therapy with classical inhibition of CTLA4 and PD-1/PD-L1 may, thus, result in a durable clinical response in cancer therapy." (PMID 36159789, 2022). "Immune checkpoint inhibitors, targeting cytotoxic T-lymphocyte-associated protein 4 (CTLA-4) and the programmed cell death protein-1 (PD-1)/programmed cell death ligand-1 (PD-L1) pathways have shown remarkable potential in several types of cancer." (PMID 35710424, 2022). "Notably, cGAS-STING-agonists act in combination with immune checkpoint targeting drugs (CTLA-4, PD-1, PD-L1) to induce potent cancer eradication." (PMID 35655772, 2022). "Thus, immune checkpoint inhibitors (ICIs) against CTLA4 and PD-1 and its ligand PD-L1, such as Ipilimumab, Pembrolizumab, Nivolumab, and Atezolizumab, have been used to treat the malignant tumors and significantly improve the survival of patients." (PMID 36119019, 2022). "Beyond the canonical immune checkpoints of CTLA4 and PD-1/PD-L1, other immune checkpoints may, therefore, also be crucial in reducing immune responses in numerous cancers." (PMID 36159789, 2022). "Immune checkpoint inhibitors targeting cytotoxic T-lymphocyte-associated protein 4 (CTLA4) and programmed cell death 1/programmed death ligand 1 (PD1/PDL1) have been used with great success in several cancers and are now widely accepted as one of the standard therapies in cancer treatment." (PMID 36048239, 2022). "Anti-CTLA-4 or anti-PD-L1/PD-1 fully humanized antibodies, which target immune checkpoint molecules expressed by cTreg cells upon activation, have shown promising results in clinical studies treating various cancer types." (PMID 35860556, 2022). "Future studies are needed to confirm whether the observed irAE/infection association is preserved in subjects administered other anti-PD-1, -PD-L1, and -CTLA-4 cancer immunotherapy." (PMID 35143542, 2022). "Finally, we reflect on the current knowledge and controversy related to reactivation of active TB in cancer patients treated with immune checkpoint inhibitors such as PD-1/PD-L1 and CTLA-4." (PMID 36591229, 2022). "Finally, immune checkpoint inhibitors, such as anti‐PD‐L1 or anti‐CTLA4, are antibodies designed to block surface receptor–ligand interactions that suppress the immune response against cancer cells." (PMID 36214609, 2022).